IL7 (interleukin 7)
Diseases named in the same sentence as IL7 in open-access papers (continued):
Sharing a sentence is not in itself a finding about the gene and the disease.
Sepsis (continued). "Immunomodulatory molecules such as IL-7, IL-15, and anti-programmed cell death 1 have been identified as potential therapeutic targets to counteract immunosuppression in sepsis." (PMID 38690455, 2024). "We established an IL-7 cutoff value of 1.94 pg/mL by comparing levels between a healthy control group and patients with sepsis (p < 0.0001)." (PMID 39684323, 2024). "We observed that on day 1, the median IL-7 levels in both the sepsis and septic shock groups were elevated, surpassing the identified cutoff value." (PMID 39684323, 2024). "Because of these functions, there have been trials investigating the therapeutic potential of IL7 in human sepsis." (PMID 38562928, 2024). "This notion has opened new lines of investigation to explore the therapeutic effects of IL-7 and other cytokine complex treatments in ameliorating sepsis-induced immune dysfunction." (PMID 36756117, 2023). "IL-7 restores T cell IFN-γ production as documented in both animal models of sepsis, in ex vivo blood studies from septic patients, and in blood samples from septic patients who were treated with IL-7 on a compassionate basis." (PMID 36906875, 2023). "IL-7 blocks sepsis-induced lymphocyte apoptotic cell death by increasing the anti-apoptotic molecule Bcl-2." (PMID 36906875, 2023). "While IL-6, PIGF, and CRP were also significantly elevated in post-Sepsis patients compared to controls, the observed differences in TNFα, Tie-2, Flt-1, IL-7 and bFGF were unique to the post-COVID group." (PMID 36844209, 2023). "Subsequently, in an ongoing phase II clinical trial including patients with sepsis administered with IL-7 treatment (NCT03821038, IRIS-7-C&D study), “lymphocyte count increased by more than 50%” was set as the primary endpoint." (PMID 36567402, 2022). "On the other hand, children with sepsis had significantly higher levels of IL-1β, IL-12 and IL-17A compared to febrile controls, whereas only levels of IL-7 were found to be significantly lower in sepsis compared to febrile controls." (PMID 35811678, 2022). "A prospective, randomized, double-blind phase II clinical trial on the efficacy of IL-7 in treating sepsis has been completed." (PMID 36209190, 2022). "Although the mechanisms are not completely understood, it is likely that IL-7 responses contribute, and phase II IL-7 trials in sepsis are ongoing." (PMID 36676685, 2022). "IL-7 is known to prevent apoptosis during sepsis by inducing increased expression of the anti-apoptotic protein Bc12." (PMID 35811678, 2022). "A recent study reported that combined treatment with IL-7 and anti-PD-1 reversed sepsis-induced T-cell exhaustion and improved survival in patients with sepsis." (PMID 35898496, 2022). "IL-7 improves ex vivo lymphocyte function, and administration of IL-7 enhances T cell receptor diversity in humans, which is typically reduced in sepsis." (PMID 33920518, 2021). "Clinically, anti-sepsis targeted therapeutic effects of IL-38 is amplified when combined with IL-5, IL-7, IL-30, and IL-33." (PMID 34830435, 2021). "Treatment of sepsis with IL-7 is promising–it was shown to be well-tolerated in clinical trials with no severe toxicities." (PMID 33920518, 2021). "Contrary to IL-7, PD-L1 has been found to have potent effects in enhancing lymphocyte death during sepsis." (PMID 34356636, 2021). "In vivo studies using a sepsis two-hit model showed that IL-7 improved the host response and had a 92% survival during sepsis." (PMID 34356636, 2021). "More importantly, clinical studies using CYT107 (recombinant IL-7) have shown reversal of the marked loss of CD4+ and CD8+ T cells following sepsis." (PMID 34356636, 2021). "Significant improvements in lymphocyte function by IL-7 have been observed in experiments involving an animal model of sepsis and using the blood of septic patients." (PMID 33679715, 2020).
Sepsis (continued). "IL-7 is also capable to prevent the sepsis-inducing depression of T-cell factors such as IFN-γ and enhance the expression of cell adhesion molecules, such as very late antigen (VLA)-4 and lymphocyte function-related antigen (LFA)-1." (PMID 32197507, 2020). "Recent studies imply that some novel immunomodulatory agents, including IL-7, IL-15, GM-CSF, IFN-γ, and co-inhibitory molecule blockade can reduce the clinical morbidity associated with severe sepsis and septic shock." (PMID 32197507, 2020). "The following contents of this review will highlight the immunomodulators that improve T cell immune responses during sepsis, such as IL-7, PD1/ PDL1-specific antibodies, IFN γ, G-CSF /GM-CSF, IL-15, IL-1ra, and anti-IL-6 antibody." (PMID 32197507, 2020). "IL-7 has a potent anti-apoptotic activity, which can abolish sepsis-induced apoptotic depletion of CD4+ and CD8+ T cells." (PMID 32197507, 2020). "In a murine model of sepsis, IL-7 treatment resulted in the upregulation of the anti-apoptotic protein Bcl-2 and downregulation of pro-apoptotic proteins such as Bim and Puma." (PMID 32197507, 2020). "Future large-scale RCTs are expected to address clinical effectiveness of IL-7 for the treatment of sepsis." (PMID 33679715, 2020). "IL-7 and anti-PD-1 or blocking IL-10 reverse sepsis-induced immunosuppression, including increasing HLA-DR expression and IFN-γ production, and improve survival in mouse models." (PMID 32983116, 2020). "In experimental models of sepsis, IL-7 was responsible for regulating BCL2 to block lymphocyte apoptosis, restoring IFN-γ production and improving recruitment of immune cells to the infection site." (PMID 32479514, 2020). "This has led to a recent trial of human recombinant IL-7 therapy to patients who had evidence of lymphopenia and persistent vasoactive medication requirements in the setting of sepsis." (PMID 31014397, 2019). "Preclinical studies have supported the use of recombinant IL-7 as an immunostimulant to improve survival in animal models of sepsis." (PMID 31014397, 2019). "IL-7 has been shown to improve survival in murine models of sepsis, and lymphocyte functions of septic patients can be restored by ex vivo stimulation with IL-7." (PMID 31373289, 2019). "On the other hand, late IL-7 treatment prolongs the sepsis induced expansion of immunosuppressive IL-10 producing B-lymphocytes and MDSC after sepsis." (PMID 30730978, 2019). "IL-7 administration is an attractive therapy in sepsis, because it blocks sepsis-induced apoptosis of immune effector cells and increases IFN-γ, a cytokine that is critical for an effective host response against invading pathogens." (PMID 31611560, 2019). "In contrast, the initial loss of lymphocytes was more than compensated in IL-7 treated septic mice, which harboured significantly more CD3+ cells in their spleen compared with sham mice d8 after sepsis induction." (PMID 30730978, 2019). "Several immunotherapies have undergone clinical trials in sepsis with promising results, including recombinant interleukin-7 (IL-7), interferon-gamma (IFN-γ), Fms-like tyrosine kinase 3 ligand, and chimeric antigen receptor T cell (CAR-T)." (PMID 31187301, 2019). "In particular, preclinical studies showed that IL-7 treatment reduced mortality in murine models of sepsis and improved cell functionality upon ex vivo activation of T lymphocytes of patients with septic shock." (PMID 30995946, 2019). "Early IL-7 treatment has been shown to improve survival in murine sepsis models and to restore normal lymphocyte counts and functions in septic patients." (PMID 30730978, 2019). "Interleukin 7 (IL-7) is important for the maintenance of lymphocytes and can accelerate the reconstitution of effector lymphocytes in sepsis." (PMID 29466409, 2018). "Early IL-7 treatment has been shown to be a promising approach in a mouse sepsis model and ex vivo studies with IL-7-treated lymphocytes from sepsis patients showed significant improvement in their function." (PMID 29466409, 2018).
Sepsis (continued). "To determine the effect of IL-7 treatment on the immunophenotype of sepsis-survivors we also analysed the effects of late-onset IL-7 treatment on the immunoregulatory cell populations." (PMID 29466409, 2018). "IL-7 is required for lymphocyte development and maintenance and sepsis induces ablation of IL-7-producing osteoblasts." (PMID 29466409, 2018). "A human clinical study shows that IL-7 gene expression is reduced during sepsis but remains surprisingly normal during bacteremia; however, IL-7 level is unchanged." (PMID 29977234, 2018). "Not only do all three agents have reported efficacy in animal infectious models, but IL-7 and anti-PD-1 reverse T cell dysfunction in ex vivo blood samples from patients with sepsis." (PMID 29944697, 2018). "The undergoing trial of GM-CSF and IL-7 during sepsis will help to have a better idea of their utility in this indication." (PMID 29977234, 2018). "Ex vivo studies of peripheral blood mononuclear cells from patients with sepsis demonstrate that IL-7 and anti-PD-1 and/or anti-PD-L1 decrease apoptotic cell death and enhance T cell IFN-γ production." (PMID 29944697, 2018). "IL-7 is essential for the development of B cells and an increase in total B cells was also seen in the IL-7 treated mice, 1 month and 3.5 months after sepsis induction." (PMID 29466409, 2018). "Remarkably, similar to our observations of DN T cells and IL-10 producing B cells, the sepsis-induced increase in this immunosuppressive cell population was further enhanced in IL-7-treated septic mice." (PMID 29466409, 2018). "The frequency and numbers of Gr1+CD11b+ cells were massively increased in the bone marrow and spleen of mice with sepsis, most prominently in the septic mice treated with IL-7, compared with sham mice." (PMID 29466409, 2018). "Animal studies of sepsis involving P. aeruginosa and S. aureus, two bacteria classified as superbugs, have shown that IL-7, anti-PD-1/L1, and OX-40 ligand restore T cell IFN-γ production, decrease bacterial load, and improve survival." (PMID 29944697, 2018). "The results are much awaited to evaluate IL-7 potential as a future tool for sepsis immunotherapy (IRIS-7-A and B trials, NCT02797431 and NCT02640807)." (PMID 29977234, 2018). "Previous studies showed that IL-7 can support immune-cell reconstitution in lymphopenic conditions, restore sepsis-induced lymphocyte dysfunctions, enhance effector function of autoreactive T cells, and expand tumor-reactive T cells." (PMID 29506153, 2018). "An increased frequency of MDSCs in the spleen was still detectable 3.5 months after sepsis induction and this was more pronounced in IL-7-treated mice." (PMID 29466409, 2018). "In this regard, CD4 T cells from animals with sepsis that were treated with IL-7 had an increase in CD28 expression and improvement in T cell function." (PMID 26786705, 2016). "Other potential immunotherapy agents, such as anti-programmed cell death ligand 1 (PD-L1) antibody and interleukin 7 (IL-7), have shown benefit in animal models of sepsis and are currently being tested in clinical trials." (PMID 27760554, 2016). "In this regard, IL-7, which potentiates T cell functions, is shown to reverse immune suppression in the context of severe sepsis." (PMID 26218271, 2015). "Because lymphocyte apoptosis has been reported in sepsis, the level of IL-7 was expected to be higher in the survival group and the LTSG." (PMID 24886652, 2014). "During experimental sepsis, IL-7 decreases cell apoptosis through the expression of antiapoptotic Bcl-2 gene." (PMID 25614712, 2014). "The reported benefit of treatments aimed at preventing early lymphocyte apoptosis in animal models of sepsis, such as the early supplementation with the pro-survival cytokines IL7 or IL15 is consistent with this notion." (PMID 25541945, 2014). "Severe sepsis differed from infection by having decreased IL7, IL23, IFNγ, and TNFα gene expression." (PMID 23935244, 2013).
Sepsis (continued). "Pre-operative IL-2 and IL-7 mRNA values of patients in the thoracic surgery study were compared with patients in the sepsis study." (PMID 21711552, 2011). "There was no relation between severity of organ failure and/or outcome in patients with sepsis and IL-2, IL-7, IL-15, Bim, Bax or Bcl-2 gene expression." (PMID 21711552, 2011). "Median Pre-operative IL-7 mRNA copy numbers were similar to those of bacteraemic patients and healthy controls, and greater than patients with sepsis (Wilcoxon rank sum test P < 0.0001)." (PMID 21711552, 2011). "In this study lymphopenic patients with severe sepsis had decreased IL-7 gene expression, compared to controls and patients with infection." (PMID 21711552, 2011). "The interaction between patient Group and Stimulus type had a significant effect on IL-7 gene expression (P = 0.04), as in the presence of CD3ab, IL-7 gene expression was greater in PBLs from patients with sepsis than in control samples (P = 0.005)." (PMID 21711552, 2011). "Recent studies have documented elevated levels of IL-1 beta, IL-6, IL-7, IL-8, IL-10, IL-13, and tumour necrosis factor-alpha in septic shock patients than in those with severe sepsis." (PMID 20490277, 2010). "In clinical settings, endogenous IL-7 and IL-7R have shown promise as prognostic markers in sepsis." (PMID 41158471, 2025). "A thorough understanding of the regulatory role of IL-7 in sepsis is essential to achieve a higher level of precision in identifying septic patients who would benefit from recombinant human IL-7 immune boosters and to determine the optimal timing for its administration." (PMID 40005375, 2025). "We included nine studies investigating the clinical application of IL-7 in sepsis." (PMID 41158471, 2025). "We found that endogenous IL-7 in the blood may serve as a marker for assessing disease severity and prognosis in elderly patients with sepsis." (PMID 41158471, 2025). "In sepsis, endogenous IL-7 levels rise from a low baseline and may remain elevated for a prolonged period." (PMID 41158471, 2025). "This article reviews the changes and effects of both endogenous and exogenous IL-7 in sepsis." (PMID 41158471, 2025). "Daily serial measurements might establish a variation curve for IL-7, which provides valuable insights into its dynamics during sepsis." (PMID 40005375, 2025). "Moreover, individuals with Alzheimer’s disease who die from sepsis have lower IL-7 levels in the brain." (PMID 41158471, 2025). "Interestingly, patients with severe sepsis display lower blood IL-7 mRNA expression than individuals with less severe disease." (PMID 41158471, 2025). "However, exogenous IL-7 has the potential to reverse immune dysfunction in patients with sepsis, although mortality rates remain unchanged." (PMID 41158471, 2025). "IL-7 contributes significantly to the progression and management of sepsis." (PMID 40386708, 2025). "Overall, endogenous IL-7 may serve as a prognostic marker in elderly patients with sepsis, whereas sIL-7R may be used to evaluate prognosis in the general sepsis population." (PMID 41158471, 2025). "Combining IL-7 with adjunctive therapies and employing precision biomarkers could unlock its full potential to transform sepsis management beyond immune reconstitution." (PMID 41158471, 2025). "Moreover, IL-7 can inhibit the massive apoptosis of immune-effector cells induced by sepsis and restore the production of IFN-γ, which is essential for the host’s response to invading pathogens." (PMID 39720718, 2024). "We conclude that IL-7 immunostimulatory therapy, whether used individually or in combination, may represent a promising and potentially protective treatment option for sepsis-induced immunosuppression." (PMID 39720718, 2024). "The intervention of IL-7 holds promise for the restoration of functional capabilities in T cells that are characterized by hyporesponsiveness or exhaustion, a common feature observed in sepsis." (PMID 38510969, 2024).
Sepsis (continued). "This has led to trials investigating the effect of IL7 in human sepsis." (PMID 38562928, 2024). "This apparent contradiction, wherein CD127-mediated pathways contribute to the progression of sepsis while IL-7 supplementation shows therapeutic benefits, may be explained by considering the temporal dynamics of sepsis." (PMID 38601150, 2024). "Additionally, potential alternative strategies such as immunostimulants like IL-15 and IL-7 are proposed to counteract the immunosuppressive state induced by sepsis, although further clinical trials are warranted to validate these approaches." (PMID 38690455, 2024). "Immunoadjuvant therapy using IL-7 and IL-15, administration of interferon γ, and targeting PD-1, particularly to septic patients who exhibit immunosuppressive tendencies, signifies a significant forthcoming breakthrough in the realm of sepsis." (PMID 38510969, 2024). "Notably, IL-7 administration has shown promise in addressing various conditions, including sepsis and HIV or hepatitis C and B infections." (PMID 39541412, 2024). "IL-7 plays a dual role in sepsis; it can also be used to guide exogen therapy with IL-7." (PMID 39684323, 2024). "This study explores the relationships between cell death biomarkers (serum-soluble levels of programmed cell death protein 1 (PD-1), programmed death ligand 1 (PD-L1), and interleukin-7 (IL-7)) and the percentages of various lymphocyte subsets in relation to the severity and progression of sepsis." (PMID 39684323, 2024). "Further research is needed to elucidate the intricate interplay between the signaling pathways mediated by CD127 and the therapeutic application of IL-7, particularly in delineating the mechanisms that govern the transition from hyperinflammation to immunosuppression in sepsis." (PMID 38601150, 2024). "Therefore, receiver operating characteristic (ROC) curve analysis was used to assess the diagnostic accuracy and determine the optimal cutpoint values for IL-7 levels between patients with sepsis/septic shock and control groups." (PMID 39684323, 2024). "The concentration of IL-7R in peripheral blood were highest in sepsis group and IL-7 antibody treatment could decrease the concentration of IL-7R." (PMID 37113759, 2023). "The concentration of IL-6 in peripheral blood were highest in sepsis group and IL-7 antibody treatment could decrease the concentration of IL-6." (PMID 37113759, 2023). "The concentration of TNF-γ in peripheral blood were highest in sepsis group and IL-7 antibody treatment could decrease the concentration of TNF-α." (PMID 37113759, 2023). "IL-7 is safe and well tolerated and is a promising new immune-adjuvant therapy for sepsis." (PMID 38114466, 2023). "The concentration of IFN-γ in peripheral blood were lowest in sepsis group and IL-7 antibody treatment could increase the concentration of IFN-γ." (PMID 37113759, 2023). "Notably, administration of IL-7 was well-tolerated in a phase II trial in sepsis patients, and reversed sepsis-induced lymphopenia and enhanced T-cell activation." (PMID 36470832, 2022). "IL-7 is perhaps the most promising potential immunotherapy for sepsis." (PMID 36389695, 2022). "Among the cytokines identified, IL-1β had the highest AUC value (0.78; p <0.001) in differentiating children with sepsis from clinical malaria, whereas IL-7 showed a greater potential in distinguishing patients with sepsis from febrile controls (AUC of 0.92, p<0.0001)." (PMID 35811678, 2022). "Lower levels of IL-7 in the sepsis group may be due to its important role in reversing the immunosuppressive state in sepsis." (PMID 35811678, 2022). "IL-7 acts extensively on cells of the adaptive immune system, promoting the proliferation and survival of primary and memory CD4+/CD8+ T cells, and can reverse the immune deficiency of sepsis." (PMID 36389695, 2022). "Thus, the hIL-7-Fc produced after MVA infection can efficiently initiate IL-7 intracellular signaling in T lymphocytes from patients with sepsis and controls." (PMID 36045686, 2022).